BMAL1 (basic helix-loop-helix ARNT like 1)
Diseases named in the same sentence as BMAL1 in open-access papers (continued):
Sharing a sentence is not in itself a finding about the gene and the disease.
tumor (continued). "It has been reported before that the circadian clock pathway is involved in cancer in addition to its key role in the regulation of circadian rhythm, while the circadian clock pathway member BMAL1 can act as either a tumor suppressor or oncogene in different malignancies." (PMID 38951864, 2024). "The reasons for diverse impacts of BMAL1 deletion in different tumor types are unclear." (PMID 39070610, 2024). "This method also significantly induced Bmal1 expression in the liver, which may act as a regulator of tumor suppression." (PMID 39272783, 2024). "CLOCK/BMAL1 induces tumour promoting inflammation whereas RORα abrogates it." (PMID 38378853, 2024). "In particular, it has been demonstrated that overexpression of CLOCK enhances the expression of genes related to angiogenesis, including vascular endothelial growth factor (VEGF), hypoxia-inducible factor 1-alpha, (HIF1α), and basic helix-loop-helix (BMAL1), which is a tumor suppressor." (PMID 38892035, 2024). "Therefore, BMAL1 emerges as a potential target in investigating tumor therapeutic strategies aimed at ferroptosis." (PMID 38703241, 2024). "Our findings suggest that decreased expression of HIF target genes could contribute to reduced growth upon BMAL1 deletion in some tumor types." (PMID 39070610, 2024). "Those few melanoma patients whose tumor was characterized with high BMAL1 mRNA expression had prolonged survival, possibly as a result of reduced key DNA-repair enzyme expressions, increased mutational/neoantigen load, and strong intratumoral T-cell infiltration and activation." (PMID 38834742, 2024). "Interestingly, this study also demonstrated that patients with higher BMAL1 expression in tumor-infiltrating lymphocytes had a better survival prognosis than patients with lower BMAL1 expression." (PMID 39272783, 2024). "Additionally, oncogenes such as MYC and N-MYC disrupt circadian rhythms by inducing REV-ERBα, which reduces BMAL1 levels and rhythmic activity, thereby impacting tumour growth and metabolism." (PMID 39566400, 2024). "Therefore, BMAL1 and cell-autonomous circadian oscillations in both DCs and T cells are critical for time-of-day differences in tumor volume." (PMID 36768253, 2023). "Notably, the roles of clock components in tumorigenesis depend on cancer cell type or status, as they (e.g., Bmal1, Clock and Cry1) exert tumor-promoting effects for some cell types such as mesothelioma, glioblastoma stem cells and leukemia stem cells." (PMID 37215573, 2023). "Additionally, CLOCK and BMAL1 overexpression can promote cancer cells growth by affecting F-actin formation, indicating that regulation of BMAL1 has diverse effects on tumor proliferation, invasion and metastasis across different oncogenic pathways." (PMID 38189049, 2023). "Protein levels of tPA and uPA were increased in tumor tissues grown in Bmal1−/− mice." (PMID 37330661, 2023). "In addition, 58.3% of patients exhibited BMAL1 positive in primary CRC tumor, which was common among younger patients (p < 0.05)." (PMID 36806631, 2023). "In different cancers, BMAL1 expression significantly differs between tumor and normal tissues." (PMID 36647780, 2023). "By day 20 after tumor implantation, an ≈70% increase of tumor mass was detected in Bmal1−/− mice." (PMID 37330661, 2023). "Furthermore, core circadian genes Per2 and Bmal1 were shown to have cell-autonomous tumor-suppressive roles in transformation and lung tumor progression." (PMID 38090501, 2023). "Bmal1 deletion also increased tumor incidence in the KrasG12D mouse lung cancer model." (PMID 37524704, 2023). "However, treatment with SB‐431542 markedly decreased lung metastasis in tumor‐bearing in Bmal1−/− mice." (PMID 37330661, 2023). "Notably, this is associated with poor prognosis and is BMAL1 dependent since ectopic expression of BMAL1 inhibits tumor growth." (PMID 37262074, 2023).
tumor (continued). "Similarly, Clec9a-cre:Bmal1flox mice, which lack Bmal1 expression in conventional DCs (Bmal1ΔcDC), showed comparable tumour size kinetics when tumour cells were inoculated either at ZT9 or ZT21." (PMID 36470303, 2023). "The balance between BMAL1 and Hif-1α affects the metabolism of macrophages and anti-tumor immunity." (PMID 36647780, 2023). "In addition, depletion of BMAL1 strongly suppresses xenograft tumor growth in mice treated with VP16." (PMID 36725890, 2023). "As expected, diurnal Bmal1 expression was disrupted in the tumor of jetlagged mice." (PMID 37215573, 2023). "In HNF4α-positive HCC, the increase in BMAL1 expression slows tumor growth in vivo, thus indicating that BMAL1 may be a potential target for reversing HNF4α-positive HCC." (PMID 36647780, 2023). "The active form of TGF‐β was markedly increased in tumor and plasma of Bmal1−/− mice." (PMID 37330661, 2023). "The formation of heterodimers between Npas2 and Arntl (Bmal1) may regulate the transcription of tumor cell growth and survival, further indicating a potential tumor-suppressing effect associated with these genes." (PMID 35457963, 2022). "Altogether, these results further confirmed the crucial anti-tumor role of BMAL1 in HCC." (PMID 36439870, 2022). "This implies a potential tumor-suppressive role for BMAL1 in HCC." (PMID 36439870, 2022). "Similarly, these tumor-derived organoids immediately grew as spheroids, which resembled the transformed morphology of late-passage Apc+/−;Bmal1−/− organoids." (PMID 35947664, 2022). "Notably, these target genes of BMAL1 were enriched in glycerolipid metabolic pathway, which plays important roles in tumor progression." (PMID 36439870, 2022). "To address this question, we first profiled changes in gene expression in early-stage Apc+/−;Bmal1−/− enteroids versus late-stage tumor spheroids to determine whether progressive changes in Wnt signaling had occurred in culture." (PMID 35947664, 2022). "To further examine the suppressive role of BMAL1 in in vivo tumor growth, we established subcutaneous xenograft tumor models by administering SNU-368 cells harboring stable BMAL1 knockdown or control cells into the left and right flanks of nude mice, respectively." (PMID 36439870, 2022). "Besides, a negative relationship between mRNA expression levels of miR-494-3p and BMAL1 was reported in tumor tissues in 30 HCC individuals." (PMID 36439870, 2022). "Notably, classical Wnt target genes Axin2 and Birc5 (also known as Survivin) were significantly up-regulated only in late-passage Apc+/−;Bmal1−/− organoids that grow as tumor spheroids." (PMID 35947664, 2022). "Mechanistically, BMAL1 regulates the PI3K-AKT signaling axis to exert tumor suppressive properties." (PMID 36467684, 2022). "We then investigated the tumor-suppressive effect of BMAL1 on cell migration and infiltration." (PMID 36439870, 2022). "Furthermore, this resistance to Beva was caused by an internal, intracellular "escape" pathway of the tumor cells that involved BMAL1." (PMID 34815366, 2021). "Consistently, the suppression of BMAL1 results in the development of the tumor." (PMID 34069297, 2021). "CLOCK and BMAL1 clock master genes may harbor tumor-suppressive functions both in humans and rodents." (PMID 33810377, 2021). "In addition, silencing BMAL1 impaired the effects of dexamethasone on tumor growth of melanoma in an in vitro experiment." (PMID 34069297, 2021). "In TH17 cells, BMAL1 and other circadian signals both positively and negatively control the balance between effector and regulatory T cells, which has direct implications for anti-tumor therapeutic strategies." (PMID 33794967, 2021).
tumor (continued). "Interestingly, phosphorylation of BMAL1 at Ser42 and total BMAL1 protein showed a circadian rhythm, so it is possible that the clock in the tumor is driven by post-translational modifications." (PMID 33495474, 2021). "Especially Per2 and BMAL1 genes have been more pronounced as tumor suppressors." (PMID 35126099, 2021). "As the core gene of rhythm gene, BMAL1 is an important regulator that maintains normal cell and tissue homeostasis and plays an extremely critical role in tumor-related processes, such as cell proliferation and apoptosis, DNA repair, metabolism, and angiogenesis." (PMID 34815366, 2021). "Collectively, our data suggest that restoration of BMAL1 is tumor suppressive in NB." (PMID 34183658, 2021). "Importantly, the anti-tumor activity of SR1078 and RORα is abolished following depletion of BMAL1, further supporting that the core clock component BMAL1 functions as a tumor suppressor in NB." (PMID 34183658, 2021). "We then explored the expression of BMAL1 protein in tumor tissue using IHC." (PMID 33528793, 2021). "Considering that REV-ERBs inhibit Bmal1 expression, agonists of these nuclear receptors could be regarded as an exciting novel approach to target Bmal1, which has been shown to have tumor-promoting features in GBM models." (PMID 34361055, 2021). "Our results showed that BMAL1 KD led to a significant reduction in proliferation (~40% reduction, p = 0.0007), induction of apoptosis (1.4-fold induction, p = 0.0152) accompanied by a reduction of tumour size (30% reduction, p = 0.0003)." (PMID 32244760, 2020). "Higher levels of Bmal1 correlate with improved patient survival across different tumours." (PMID 35582450, 2020). "To confirm that macrophage Bmal1 modulates tumor growth cell-autonomously and to assess the effect of TAMs on anti-tumor immune response within the same host environment, we co-injected B16-F10 cells with either WT or M-BKO macrophages into the right or left flanks, respectively, of WT mice." (PMID 32396064, 2020). "Given that the YY1 induction of miR-135b suppresses Bmal1, as shown in pancreatic cancers, YY1 may be important to the loss of circadian regulation of metabolism that is proposed to underpin tumour aetiology as well as ongoing tumour pathophysiology." (PMID 35582450, 2020). "To determine whether BMAL1 was reduced only by tumor acidosis, we adjusted the pH of the cell culture medium using HCl." (PMID 32316196, 2020). "Although BMAL1 is known to inhibit tumor progression, the mechanism for decreasing BMAL1 in cancer is largely unknown." (PMID 32316196, 2020). "Notably, a decrease of BMAL1 by tumor acidosis was recovered by the exchanging acidic cultured media to fresh media or adding NaHCO3 to the acidic cultured media." (PMID 32316196, 2020). "Since previous studies have reported that circadian genes including BMAL1 are reduced in almost cancers, we hypothesized that tumor hypoxia, a common and predominant occurrence in cancer, plays a critical role in decrease of the BMAL1 circadian gene." (PMID 32316196, 2020). "BMAL1 could be maintained in a tumor acidic pH by selectively targeting for acidosis via buffering the increased protons using NaHCO3 or inhibiting anaerobic glycolysis enzymes such as LDH-A using melatonin." (PMID 32316196, 2020). "Consequently, the YY1-miR-135b suppression of Bmal1 is likely to be an important aspect of how alterations in mitochondrial metabolism occur in the tumour microenvironment." (PMID 35582450, 2020). "Therefore, we proposed a new mechanism for melatonin, which regulates BMAL1 expression during hypoxia-mediated tumor acidosis by inhibiting LDH-A." (PMID 32316196, 2020). "Altogether these results suggest that BMAL1 may exert both protective and pro-tumor effects based on the different cellular contexts and on the activation of circadian dependent or independent functions of the BMAL1 gene in different organs." (PMID 33114365, 2020).
tumor (continued). "Another study indicated that decreased BMAL1 expression accelerates tumor development and might influence the body’s response to anticancer drugs." (PMID 33114496, 2020). "Studies have found that BMAL1 may play an opposite role in different cancers, and it may regulate the proliferation of tumor cells through different pathways." (PMID 31346317, 2019). "In a word, our studies showed that BMAL1 could promote the tumor metastasis by increasing the expression of MMP9 at mRNA and protein levels." (PMID 31346317, 2019). "Therefore, when the expression of Bmal1 and Per2 genes is downregulated, tumour cells will grow and proliferate rapidly." (PMID 31744421, 2019). "Furthermore, these data reveal that forced expression of BMAL1 inhibits HNF4α-positive tumor growth." (PMID 30341289, 2018). "Per2 and BMAL1 lose the ability of inhibiting tumor progression and hence promotes lung cancer." (PMID 29607311, 2018). "Additionally, there is evidence showing that both oncogenes and tumor-suppressor genes are regulated by CLOCK and BMAL1 in tumor cells, which indicates regulatory roles of those two proteins in cancers." (PMID 30287810, 2018). "However, the roles of the CLOCK and BMAL1 genes in the regulation of tumor progression via the RHOA-ROCK-CFL pathway remain largely unclear." (PMID 30287810, 2018). "Importantly, multivariate Cox regression adjusting for age, gender, tumor pathologic stage, ulceration status, mitotic count, and Breslow thickness revealed BMAL1 expression as an independent prognostic factor." (PMID 29946530, 2018). "Thus, we conclude that the co-expression of P2-HNF4α and BMAL1 in HCC is incompatible with tumor cell proliferation in vitro and in vivo." (PMID 30341289, 2018). "Interestingly, double mutation of cryptochromes (Cry1,2−/−), Periods (Per1,2−/−), or Bmal1 in the liver (Albcre; Bmal1fl/fl) accelerates progression of these symptoms and increases tumor incidence." (PMID 28425940, 2017). "PER and BMAL1 have also been identified as tumour suppressors." (PMID 27465361, 2016). "Accumulative evidence has shown that Bmal1 and RORα are tumor suppressors." (PMID 27602774, 2016). "It is also possible that the clock genes Clock, Cry1 and Bmal1, which are involved in the circadian control of whole-body glucose metabolism, may have contributed to the circadian regulation of tumor glucose metabolism in our investigation." (PMID 25099274, 2014). "Based on a recent report that downregulation of Bmal1 promotes tumor growth in cell culture and mice, we herein investigated whether Bmal1 also influences the invasiveness of cancer cells." (PMID 23563360, 2013). "Collectively, our data suggest that Bmal1 is a tumor suppressor, capable of suppressing cancer cell growth and invasiveness, and support the recent proposal that there is a tight molecular link between circadian rhythms and tumor formation/progression." (PMID 23563360, 2013). "Together, these reports and our present results suggest that Bmal1 functions as a tumor suppressor." (PMID 23563360, 2013).
tumor (continued). "While the circadian genes PER1 and PER2 have been clearly shown to function as tumor suppressors in the mouse model, a recent study showed that epidermal deletion of BMAL1 in a transgenic mouse model which spontaneously develops squamous tumours leads to significantly fewer neoplastic lesions." (PMID 22470559, 2012). "A sublethal dose of γ-Radiation induced premature aging on the external appearance of all circadian gene-mutant mouse models studied and further increased incidence of tumor and hyperplasia as well as ulcerative dermatitis in Bmal1+/−, Per- and Cry-mutant mice." (PMID 20539819, 2010). "Irradiated Bmal1+/− mice showed a similar rate of tumor development as did irradiated Per2−/− mice." (PMID 20539819, 2010). "At 2 and 14 HALO, tumor size is low, which is also when nuclear BMAL1 is high." (PMID 19688113, 2009). "Importantly, circadian BMAL1 expression was in tumour of a mouse model followed by TYMS expression and combined overexpression correlated to low response and worse survival on 5-Fu treatment." (PMID 19662092, 2009). "Consequently, we investigated whether re-modulating the nuclear accumulation of p62 could inhibit tumor cell growth mediated by BMAL1." (PMID 40638681, 2025). "Subsequent to the completion of tumor modeling, the mice were individually administered with venetoclax, dasatinib, and sorafenib.The administration of venetoclax, dasatinib, and sorafenib demonstrated significant efficacy in reducing tumor size in mice harboring BMAL1 knockdown cells." (PMID 38703241, 2024). "This may explain why BMAL1 has distinct roles in tumor proliferation and chemoresistance." (PMID 36725890, 2023). "RORα and BMAL1 may mediate its inhibitory effect on tumor growth." (PMID 36647780, 2023). "Furthermore, the in vivo tumor-suppressive effects of BMAL1 over-expression were also determined." (PMID 36439870, 2022). "Also, the expression of pro-apoptotic proteins was increased while the anti-apoptotic protein BCL-2 level decreased, suggesting that BMAL1 may operate as a tumor-suppressor in U-87MG cell cultures." (PMID 34361055, 2021). "Additionally, BMAL1 knockdown impaired proliferation of patient-derived GSCs in culture, inducing cell cycle arrest and apoptosis as well as extending the life span and inhibiting tumor growth in a murine model." (PMID 34361055, 2021). "However, depending on the model and the tissue, CLOCK and BMAL1 may be oncogenic or tumor suppressive." (PMID 33810377, 2021). "It was also proposed that BMAL1 may act as a tumor suppressor in GBM cell growth." (PMID 34361055, 2021). "Therefore, the anti-tumor effect of cisplatin may be still preserved when we manipulate the local diurnal expression of Bmal1 in the kidney to avoid the toxic side-effect of cisplatin." (PMID 32522976, 2020). "We hypothesized that melatonin might prevent the decrease of BMAL1 by tumor acidosis." (PMID 32316196, 2020). "Furthermore, several reports have indicated that BMAL1 could increase the sensitivity of malignant tumor cells to chemotherapeutics." (PMID 32231148, 2020). "Accordingly, BMAL1 may act as a tumor suppressor, inhibits the growth and invasion of cancer cells." (PMID 32195174, 2020). "In an earlier study, Bmal1 has been found associated with tumor suppression 47; hence its non-functionality may upregulate oncogenes." (PMID 31523185, 2019). "Our finding that BMAL1 deletion increases sensitivity to chemotherapeutic agents suggests that interfering with BMAL1 expression might have a protective or preventive function against tumor initiation following repeated DNA damage insults." (PMID 30375470, 2018). "Thus, to examine whether CLOCK and BMAL1 can promote tumor cell proliferation via RHOA, the Cell Counting Kit-8 assays were introduced to observe cell proliferation in HeLa cells." (PMID 30287810, 2018).